POLDIP2 (DNA polymerase delta interacting protein 2)
Description:
Involved in DNA damage tolerance by regulating translesion synthesis (TLS) of templates carrying DNA damage lesions such as 8oxoG and abasic sites. May act by stimulating activity of DNA polymerases involved in TLS, such as PRIMPOL and polymerase delta (POLD1).
Synonyms: p38; PDIP38; DKFZP586F1524
Tractability: PROTAC: ubiquitination databases record sites on it; its protein half-life has been measured.
Gene: Protein-coding gene on chromosome 17 (28,346,173 to 28,357,584, reverse strand). Ensembl gene ENSG00000004142.
Subcellular location: Mitochondrion matrix; Nucleus
Subcellular location (Human Protein Atlas): Mitochondria
Gene Ontology:
Molecular function: protein binding; protein-macromolecule adaptor activity; DNA binding
Biological process: error-free translesion synthesis
Cellular component: mitochondrial matrix; mitochondrial nucleoid; mitochondrion; nucleus
Genetic constraint (gnomAD): Loss-of-function variants: 20 observed, 27.28 expected, observed/expected ratio (o/e) 0.73, 90% interval 0.51 to 1.07. The upper end of that interval is the gene's LOEUF score, 1.07, which puts it in group 4 of 6, group 1 being the genes least tolerant of losing a copy. Missense variants: 262 observed, 315.08 expected, observed/expected ratio (o/e) 0.83, 90% interval 0.75 to 0.92. Synonymous variants: 126 observed, 115.29 expected, observed/expected ratio (o/e) 1.09, 90% interval 0.94 to 1.27.
Homologues: Orthologues: chimpanzee POLDIP2 (99% identical), macaque POLDIP2 (98% identical), rabbit POLDIP2 (98% identical), dog POLDIP2 (97% identical), pig POLDIP2 (97% identical), guinea pig POLDIP2 (96% identical), mouse Poldip2 (95% identical), rat Poldip2 (87% identical), tropical clawed frog poldip2 (85% identical), zebrafish poldip2 (78% identical), Drosophila melanogaster POLDIP2 (59% identical), Caenorhabditis elegans tag-307 (33% identical). Paralogues in human: FBXO3 (21% identical).
Diseases named in the same sentence as POLDIP2 in open-access papers:
POLDIP2 is named in the same sentence as 34 diseases in open-access papers, as found by Europe PMC text mining. Sharing a sentence is not in itself a finding about the gene and the disease. The quoted sentences say what the papers report.
breast carcinoma (5 papers, 2010 to 2022). "The TNFAIP1/POLDIP2 CSAGA is a clinically relevant transcriptional structural-functional gene module linked to erb-b2 receptor tyrosine kinase 2 (ERBB2) amplicon core gene expression in breast cancer and connected with amplification of the genomic region on 17q11.2." (PMID 36425112, 2022). "Multiple records in the ClinVar database are currently associated with pathologies and one publication reports that amplification of Poldip2 and four adjacent genes correlates with poor prognosis in breast cancer progression." (PMID 34928942, 2021). "The role of Poldip2 in tumor formation is not well known yet, although a study of the sense-antisense gene pair of TNFAIP1/POLDIP2 found poor prognosis in breast cancer patients with upregulated Poldip2 expression." (PMID 24797518, 2014). "Correlation analysis of the TNFAIP1/POLDIP2 SFGM in four grades of breast cancer (G1, G1-like, G3-like and G3) revealed a strengthening of the correlations between the genes of the TNFAIP1/POLDIP2 SFGM." (PMID 20158880, 2010). "TNFAIP1/POLDIP2 CSAGA maps the risks of breast cancer relapse onto the complex genomic locus on 17q11.2." (PMID 20158880, 2010). "Survival analysis of a group of 410 breast cancer patients revealed significant survival-associated individual genes and gene pairs in the TNFAIP1/POLDIP2 CSAGA." (PMID 20158880, 2010). "It is important to note that the TNFAIP1/POLDIP2 module is located outside of the well-known ERBB2 amplicon on 17q12, over-representation of which in the genome is often associated with the occurrence of the ERBB2-positive breast cancer subtype." (PMID 20158880, 2010). "Finally, direct and independent evidence of the TNFAIP1/POLDIP2 SFGM activation in breast cancer cells comes from the custom track for RNA polymerase II binding in the MCF7 breast cancer cell line (black arrows)." (PMID 20158880, 2010). "We analyzed the TNFAIP1/POLDIP2 CSAGA on 17q11.2 in two breast cancer cohorts." (PMID 20158880, 2010). "Overexpression of POLDIP2, a mitochondrial protein, can increase mitochondrial lipoacylation, enhance cell respiration, and reduce the growth rate of cancer cells, thereby indicating the key role of POLDIP2 in hypoxia and metabolic adaptation of breast cancer cells." (PMID 36425112, 2022). "We suggest that the TNFAIP1/POLDIP2 CSAGA represents a clinically significant transcriptional structural-functional gene module associated with amplification of the genomic region on 17q11.2 and correlated with expression ERBB2 amplicon core genes in breast cancer." (PMID 20158880, 2010). "Therefore, we suggest that the TNFAIP1/POLDIP2 SFGM could be used potentially as a new integrative indicator in breast cancer diagnosis, prognosis and treatment monitoring." (PMID 20158880, 2010). "Correlation matrix analysis with these 38 cell lines confirmed the clear co-regulatory pattern of the TNFAIP1/POLDIP2 SFGM, which was primarily identified in two breast cancer cohorts." (PMID 20158880, 2010). "We produced correlation tables that included both the genes of the TNFAIP1/POLDIP2 SFGM and the ERBB2 CR and their neighboring genes in the Uppsala and Stockholm breast cancer cohorts." (PMID 20158880, 2010). "Therefore, the TNFAIP1/POLDIP2 SFGM is also potentially regulated by STAT1 and Sp1 as well as stimulated by interferon-gamma in breast cancer cells." (PMID 20158880, 2010). "We characterize five genes (TMEM97, IFT20, TNFAIP1, POLDIP2 and TMEM199) organized in a CSAGA on 17q11.2 (we term this the TNFAIP1/POLDIP2 CSAGA) and demonstrate their strong and reproducible co-regulatory transcription pattern in breast cancer tumours." (PMID 20158880, 2010). "Preliminary data obtained in our pilot study (not shown) indicate that the TNFAIP1/POLDIP2 SFGM demonstrates stronger correlation pattern not with the ERBB2 breast cancer subtype but rather with luminal A and B subtypes." (PMID 20158880, 2010).
breast carcinoma (continued). "Therefore, the expression profiles of the genes of the TNFAIP1/POLDIP2 SFGM and the ERBB2 CR are correlated in breast cancer and this fact could probably be explained by co-amplification of their genomic regions." (PMID 20158880, 2010). "Therefore, our survival analysis of the TNFAIP1/POLDIP2 SFGM and its "neighbouring genes" has revealed individual survival significant genes as well as significant gene pairs suggesting that the TNFAIP1/POLDIP2 SFGM is important for breast cancer prognosis." (PMID 20158880, 2010). "Similarly, in 38 breast cancer cell lines, the expression of the ERBB2 gene was significantly correlated with the expression of all the 5 members of the TNFAIP1/POLDIP2 SFGM, although the total number of observed significant correlations was less than for the breast cancer patients." (PMID 20158880, 2010). "Also, significant differences in gene expression levels were observed for TMEM97 and POLDIP2 in different grades of breast cancer in both cohorts (not shown)." (PMID 20158880, 2010). "Moreover, we suggest that the co-regulatory pattern of the five member genes of the TNFAIP1/POLDIP2 SFGM could originally be established as the result of epigenetic modifications and/or transcriptional activation rather than by recurrent amplification in breast cancer cells." (PMID 20158880, 2010).
ischemic stroke (5 papers, 2018 to 2022). A stroke disorder caused by obstruction of blood flow to the brain, due to thrombotic (local blood clot formation) or embolic (due to a blood clot or other material traveling from another site) event. "Furthermore, Hernandes's study reported that Poldip2 mediates the breakdown of BBB by MMPs activation following ischemic stroke, and another study showed that loss of Poldip2 impaired MMPs activity in a hindlimb ischemic animal model." (PMID 32790044, 2020). "POLDIP2 is upregulated following ischemic stroke and mediates the breakdown of the blood–brain barrier (BBB) by increasing cerebral cytokine production and MMP activation." (PMID 36425112, 2022). "POLDIP2 is upregulated following ischemic stroke and mediates the breakdown of the blood–brain barrier (BBB) by boosting cerebral cytokine production and MMP activation." (PMID 36425112, 2022). "ICAM-1, VCAM-1, and E-selectin mRNA levels were significantly attenuated in Poldip2+/− animals following ischemic stroke compared to sham controls." (PMID 33692398, 2021). "The upregulation of polymerase δ‐interacting protein 2 (Poldip2) was involved in aggravating BBB disruption following ischemic stroke." (PMID 32790044, 2020). "The protective effect of Poldip2 silencing in this LPS model of SAE is in agreement with our previous report that Poldip2 mediates BBB disruption following ischemic stroke." (PMID 31779628, 2019). "Poldip2 is upregulated following ischemic stroke and mediates the breakdown of the BBB by increasing cerebral cytokine production and MMP activation." (PMID 29452577, 2018). "Knowing that increased Poldip2 accounted for the breakdown of the BBB following ischemic stroke 24 and considering the astrocytic expression of Poldip2 in our study, we investigated the effect of Poldip2 upregulation on BBB integrity and brain edema formation in the BM model." (PMID 32790044, 2020). "A recent study by Hernandes demonstrated that Poldip2 was upregulated following ischemic stroke." (PMID 32790044, 2020). "Thus, Poldip2 could be a therapeutic target to improve morbidity following ischemic stroke." (PMID 33692398, 2021). "Previous work from our group has demonstrated that Poldip2 depletion attenuates TNF and IL-6 levels following ischemic stroke, possibly via regulation of NFκB33." (PMID 33692398, 2021). "Depletion of polymerase δ-interacting protein 2 (Poldip2) has previously been reported to attenuate BBB disruption, possibly via regulation of NF-κΒ, in response to ischemic stroke." (PMID 31779628, 2019).
acute respiratory distress syndrome (4 papers, 2022 to 2026). Progressive and life-threatening pulmonary distress in the absence of an underlying pulmonary condition, usually following major trauma or surgery. "It was demonstrated that Poldip2 deficiency protects against lung edema and vascular inflammation through suppressing mitochondrial ROS in a mouse model of acute respiratory distress syndrome." (PMID 36795578, 2023). "Poldip2 is involved in β2-integrin activation during the inflammatory response, which in turn mediates neutrophil-to-endothelium adhesion in lipopolysaccharide-induced acute respiratory distress syndrome." (PMID 36425112, 2022). "Polymerase delta-interacting protein-2 (Poldip2) mediates lung inflammation and vascular permeability after lipopolysaccharide-induced acute respiratory distress syndrome; however, whether it also affects the pathological consequences of SARS-CoV-2 infection is completely unknown." (PMID 42054341, 2026). "In addition, a recent study demonstrated that reduced Poldip2 protects against LPS induced-acute respiratory distress syndrome (ARDS) through suppressing mitochondrial ROS production in a mouse model." (PMID 35140544, 2022).
atherosclerosis (3 papers, 2014 to 2023). A disease characterized by the build-up of fatty material and calcium deposition in the arterial wall resulting in partial or complete occlusion of the arterial lumen. "Because it affects the cell cycle, Poldip2 is a potential novel target for treating proliferative conditions such as cancer, atherosclerosis and restenosis." (PMID 24797518, 2014). "The authors suggest that Poldip2 may be a novel therapeutic target for vascular pathologies with a significant vascular smooth muscle cell migratory component, such as restenosis and atherosclerosis." (PMID 36782330, 2023).
Encephalopathy (3 papers, 2019 to 2022). Encephalopathy is a term that means brain disease, damage, or malfunction. "Over the years, Poldip2 is emerging as an important mediator in inflammatory diseases, including sepsis-associated encephalopathy and ARDS." (PMID 35140544, 2022). "Poldip2 depletion blocks LPS-induced BBB permeability in a mouse model of sepsis-associated encephalopathy, likely through its effects on NF-κΒ/Cox-2/PGE-2 signaling." (PMID 31779628, 2019).
ischemia (3 papers, 2018 to 2022). A hypoperfusion of the BLOOD through an organ or tissue caused by a PATHOLOGIC CONSTRICTION or obstruction of its BLOOD VESSELS, or an absence of BLOOD CIRCULATION. "We made a similar observation in a hind limb ischemia model, where MMP-2 and MMP-9 activity were decreased in Poldip2+/− mice when compared to Poldip2+/+ mice 21 days after ischemia." (PMID 29452577, 2018). "Similarly, ICAM-1 and VCAM-1 mRNA levels were increased in the brain tissue of Poldip2+/+ mice after ischemia, but not in Poldip2+/− mice." (PMID 33692398, 2021).
Sepsis (3 papers, 2019 to 2022). Sepsis is defined as life-threatening organ dysfunction caused by a dysregulated host response to infection. "Thus, Poldip2 may be an important therapeutic target in the prevention of sepsis-induced BBB permeability." (PMID 31779628, 2019). "Consequently, targeted inhibition of Poldip2 may provide clinical benefit in the prevention of sepsis-induced BBB disruption." (PMID 31779628, 2019). "Poldip2 heterozygous mice exhibit reduced BBB permeability, as well as reduced cortical levels of NF-κΒ subunit p65, Cox-2, and PGE2, following LPS-induced sepsis." (PMID 31779628, 2019).
brain edema (2 papers, 2018 to 2020). Increased intracellular or extracellular fluid in brain tissue. "Both Poldip2 siRNA and UK383367 improved neurobehavioral outcomes, alleviated brain edema, preserved the integrity of BBB, and relieved the loss of AQP4 polarity in BM model." (PMID 32790044, 2020). "Therefore, Poldip2 appears to be a promising novel target for the development of therapeutic strategies to prevent the development of cerebral edema in the ischemic brain." (PMID 29452577, 2018).
Cerebral ischemia (2 papers, 2018 to 2021). Restriction of arterial blood supply to the brain associated with insufficient oxygenation to support the metabolic requirements of the tissue. "Cerebral ischemia was induced in Poldip2+/+ and Poldip2+/− mice and brains were isolated and processed for flow cytometry or RT-PCR." (PMID 33692398, 2021). "P-selectin mRNA levels remained unchanged in the brain tissue upon cerebral ischemia induction in both Poldip2+/+ and Poldip2+/− mice." (PMID 33692398, 2021). "Our results show an overall reduction in CD45+, CD45high lymphocyte, CD11b+CD45+ myeloid cell, as well as Ly6ChighCD45high and MHCIIlowCD45high inflammatory monocyte/macrophage in brains of Poldip2+/− mice 48 h after cerebral ischemia induction." (PMID 33692398, 2021). "This study aimed to define the role of Poldip2 in mediating vascular inflammation and leukocyte recruitment following cerebral ischemia." (PMID 33692398, 2021). "We propose that Poldip2 is an important regulator of the disruption of the BBB in cerebral ischemia and represents a potentially druggable target to improve edema and mortality induced by stroke." (PMID 29452577, 2018). "The fact that Poldip2 downregulation failed to abrogate induction of transforming growth factor-β suggests that Poldip2 specifically affects secretion of only certain cytokines following cerebral ischemia." (PMID 29452577, 2018). "Nonetheless, protection against BBB permeability is likely to be physiologically important, given the decreased mortality and improved motor function in Poldip2+/− mice compared to Poldip2+/+ mice 24 h after cerebral ischemia." (PMID 29452577, 2018). "TNF-α, IL-6, MCP-1, VEGF, and MMP expression induced by cerebral ischemia was abrogated in Poldip2+/− mice." (PMID 29452577, 2018). "In conclusion, we demonstrate that Poldip2 has a crucial role in increasing late BBB permeability following cerebral ischemia." (PMID 29452577, 2018). "Poldip2+/− mice presented significantly improved motor performance 6 and 24 h following cerebral ischemia induction when compared to Poldip2+/+ mice." (PMID 29452577, 2018). "Our results further suggest that increased expression of Poldip2 following the onset of cerebral ischemia leads to a Poldip2-regulated pro-inflammatory response in astrocytes and likely other cell types, increasing the late-phase permeability of the BBB." (PMID 29452577, 2018). "Poldip2 downregulation in RBMECs significantly decreased TNF-induced THP-1 adherence, suggesting that Poldip2 in endothelial cells may play a role in regulating leukocyte adhesion during cerebral ischemia." (PMID 33692398, 2021). "We then tested whether Poldip2 depletion affects the lesion volume following cerebral ischemia induction." (PMID 33692398, 2021). "Additionally, the infiltration of CD45+CD11b+ myeloid cells, Ly6ChighCD45high and MHCIIlowCD45high inflammatory monocytes/macrophages was significantly reduced in Poldip2+/− mice after cerebral ischemia when compared to Poldip2+/+ mice." (PMID 33692398, 2021). "In order to determine whether the improved response to cerebral ischemia was related to baseline structural and functional differences in Poldip2+/− mice, micro-CT and electron microscopy studies were used to visualize the brain vasculature." (PMID 29452577, 2018). "We investigated the role of Poldip2 in the late BBB permeability induced by cerebral ischemia." (PMID 29452577, 2018). "In the present study, we found an increase in both MMP-2 and MMP-9 mRNA and a clear increase in MMP-9 activity in Poldip-2+/+ mice but not in Poldip2+/− mice, implying that reduction in MMP activity may contribute to the reduced BBB permeability in Poldip2+/− mice after cerebral ischemia." (PMID 29452577, 2018). "Herein we report that Poldip2+/− mice exhibit reduced infiltration of leukocytes into the brain, as well as lower VCAM-1 expression, following cerebral ischemia." (PMID 33692398, 2021).
Cerebral ischemia (continued). "Twenty-four hours after cerebral ischemia induction, a dramatic increase in GFAP immunoreactivity was observed in the peri-infarct penumbra cortex in Poldip2+/+ mice." (PMID 29452577, 2018). "Our data show that Poldip2+/− mice had reduced mortality and BBB permeability after cerebral ischemia." (PMID 29452577, 2018). "As expected, increased Evans blue staining was observed in the brains of Poldip2+/+ mice, which is indicative of severe late BBB disruption following cerebral ischemia." (PMID 29452577, 2018). "Our data thus suggest that Poldip2 represents a novel mediator of BBB function and dynamics at a late phase following cerebral ischemia, at least in part via cytokine release in astrocytes." (PMID 29452577, 2018). "The decreased permeability observed in Poldip2+/− mice after tMCAO was further confirmed by horseradish peroxidase extravasation (data not shown) as well as in an alternative cerebral ischemia model induced by temporary unilateral carotid artery ligation followed by 7.5% hypoxia induction." (PMID 29452577, 2018). "Quantitative flow cytometric analysis of CD45 expression, a leukocyte common antigen, performed 48 h after cerebral ischemia induction, demonstrated that the number of CD45+ cells was dramatically increased in the brains of Poldip2+/+, but not in Poldip2+/− mice." (PMID 33692398, 2021).
non-small cell lung carcinoma (2 papers, 2021 to 2022). A group of at least three distinct histological types of lung cancer, including non-small cell squamous cell carcinoma, adenocarcinoma, and large cell carcinoma. "Gene analyses from peripheral blood mononuclear cells have shown that POLDIP2 mRNA expression was negatively correlated with the risk of non-small cell lung cancer (NSCLC)." (PMID 36425112, 2022). "In a previous study on non-small cell lung carcinoma (NSCLC), POLDIP2 expression was lower in NSCLC tumor tissues, but the overexpression of POLDIP2 increased the growth and invasiveness of NSCLC cell lines." (PMID 34359790, 2021).